PIK3CA (phosphatidylinositol-4,5-bisphosphate 3-kinase catalytic subunit alpha)
Diseases named in the same sentence as PIK3CA in open-access papers (continued):
Sharing a sentence is not in itself a finding about the gene and the disease.
tumor (continued). "Evolution of tumor volume prior and after calibration was compared to the experimental data used for calibration for each of the four scenarios: EGFR mutation with or without gefitinib, EGFR and PIK3CA mutation with or without gefitinib." (PMID 35796890, 2022). "Furthermore, we collected tumor tissues from 30 CRC patients with PIK3CA mutations and 30 patients without PIK3CA mutations, and analyzed the expression pattern of circLHFPL2 in these tissues." (PMID 35619132, 2022). "However, in line with current state-of-the-art molecular genotyping in NSCLC, a negative PIK3CA plasma test should be followed by profiling in tumour tissue due to assay sensitivities." (PMID 35347327, 2022). "Finally, adoptive transfer of TCR-engineered T cells led to tumor regression in vivo in mice bearing PIK3CA-mutant tumors but not wild-type PIK3CA tumors." (PMID 35484264, 2022). "In vivo, cells expressing activated PIK3CA did not form tumours that grew faster than the control models; however, they demonstrated loss of markers of well-differentiated thyroid cells, suggesting that the introduction of activated PIK3CA contributed to cellular dedifferentiation." (PMID 35193694, 2022). "Based on previous literature and our study, we speculated that psoralen inhibited the proliferation and migration ability of tumor cells, promoted apoptosis, and blocked the cell cycle by reducing the expression levels of four genes: JAK2, PIK3CA, PIK3CB, and PIK3CG." (PMID 36065261, 2022). "Additionally, we found that the status of Fusobacteria was associated with the age of the patients, tumor diameter, and MSI status, but not with genetic mutations in KRAS, NRAS, BRAF, and PIK3CA." (PMID 34650531, 2021). "Missense mutations in DDR2 (L610F), BRAF (G15V), FGFR2 (F645L), MET (T992I), NRAS (A155T) and PIK3CA (G106V) could each be outlined in one (3.7%) of the tumor specimens, respectively, but none of these were co-occurring in one and the same biopsy sample." (PMID 33572278, 2021). "Similarly, in the Cancer Genome Atlas, the OS of the PIK3CA‐mutant HER2+ tumours got a better trend than that of the PIK3CA‐WT tumours, although there was no statistically significant (Broad Institute)." (PMID 34842356, 2021). "PIK3CA was not expressed in CAFs, but the tumor cells expressed PIK3CA." (PMID 33799788, 2021). "Additionally, it was found that the abundance of Fusobacteria in CRC tumor tissues was associated with MSI status, but not KRAS, NRAS, BRAF, and PIK3CA gene status." (PMID 34650531, 2021). "Genes upregulated in both tumor and TAS of BA PCa patients as compared to WA included cell cycle markers CD19, CD2, CD53 and CD80, interferon response factor 8 (IRF8), phosphoinositide 3-kinase (PIK3CA), mechanistic target of rapamycin (mTOR), and metastasis-associated protein S100A4." (PMID 34316327, 2021). "However, amplification of EGFR, MET, and PIK3CA appear to be subclonal, in which all 3 oncogenes are coamplified within the same tumor cells as opposed to being each individually amplified across mutually exclusive clonal populations." (PMID 32338752, 2020).
tumor (continued). "Tumor purity scores, calculated using the ESTIMATE tool, were associated with FGFR3, but not PIK3CA or TERT mutations, which could be explained by a positive association between the Uro subtype and tumor purity." (PMID 31609466, 2020). "In addition, they indicated that, the detection rates of PIK3CA and/or KRAS ctDNA mutations were associated with the advanced stage; however, they were not related to the histologic subtype or residual tumor status." (PMID 33076944, 2020). "Furthermore, we found that PI3Ki and CDK 4/6 inhibitors have a synergistic anti-tumor effect when combined in human papillomavirus (HPV)-negative/PIK3CA-WT tumors." (PMID 33036331, 2020). "Mutant PIK3CA-induced constitutive PI3K activation has been shown to be essential for tumor initiation in mouse models of breast cancer and able to dedifferentiate normal lineage-restricted cells by reactivation of multi-potency at early stage of tumor initiation." (PMID 33194730, 2020). "In addition, other potential therapeutic targets, such as PIK3CA and JAK2, may be explored in EBV-positive tumours." (PMID 31790410, 2019). "However, in case 2, a lack of PIK3CA mutations was found in the post-FOLFOX metastatic samples, although the PIK3CA E542K and E88Q mutations were detected in both the primary tumor and pre-FOLFOX metastatic samples." (PMID 30898102, 2019). "Interestingly, although the specific mutations in PIK3CA are the same as those found in tumours, PROS and PIK3CA-driven vascular malformation conditions do not appear to be associated with an increased risk of cancer." (PMID 31018529, 2019). "Similarly, biomarker analysis of MONALEESA-3 demonstrated consistent benefit from ribociclib plus fulvestrant, irrespective of PIK3CA alteration status, as detected in baseline circulating tumor DNA." (PMID 31396487, 2019). "In HR−/HER2− (TNBC) tumors, PIK3CA E545K MF was positively correlated with nodal involvement (r = 0.96, p ≤ 0.001), and HRAS G12D MF was positively correlated with menopausal status and maximum tumor dimension (r = 0.85, p ≤ 0.001; and r = 0.55, p ≤ 0.05, respectively)." (PMID 30813596, 2019). "Similarly, in human HCC cell lines, silencing of SGK3 reduced PIK3CA(E545K) -but not PIK3CA(H1047R)- induced accelerated tumor cell proliferation." (PMID 30975125, 2019). "In addition, the associations of LUNAR1 with sex, age, tumour location, MSI, KRAS mutation, BRAF mutation, and PIK3CA mutation were not statistically significant." (PMID 31882986, 2019). "Because we were interested in the effect of mTORC2 signaling on the therapeutic efficacy of PI3K inhibition in HNSCC tumor cells, we made use of the cBioPortal interface to evaluate whether aberrations in these genes (RICTOR and PIK3CA) tend to co‐occur or be exclusive from one another." (PMID 31393061, 2019). "Moreover, we demonstrated that aminooxyacetate (AOA), a pan-aminotransferase inhibitor, suppresses xenograft tumor growth of PIK3CA-mutant CRC, but not PIK3CA wild type (PIK3CA WT) CRC12." (PMID 31844152, 2019). "While overexpression of p-S6 (Ser 235/236) was elevated in the two patients harbouring PIK3CA mutations, staining intensity of p-AKT, p-mTOR, p-S6 (Ser 235/236), p-S6 (Ser 240/244) and p-4EBP1 did not correlate across the tumours, indicating a complex mode of pathway activation." (PMID 29527009, 2018).
tumor (continued). "Although the response to MK2206 in vitro was highly increased in cell lines harbouring PIK3CA or PTEN mutations, tumour responses could not be linked to the presence of mutations in PIK3CA21,43." (PMID 30337563, 2018). "Taken together, in all three models, the most efficient growth inhibition of xenografts was achieved with a combination C-KRAS/PIK3CA-esiRNA, indicating that the combined inhibition of two branches of the EGFR-signaling pathway is very effective in slowing down tumor growth." (PMID 30001368, 2018). "However, in cohort 2, primary tumor location and tumor behavior, except vascular invasion and MSI, were not significantly different according to PIK3CA mutation status." (PMID 29207615, 2017). "Beside p.T790MEGFR and MUTKRAS, other mechanisms of acquired resistance not evaluated in our study have been described in tumor re-biopsies after EGFR-TKI progression, including actionable mutations of MET, HER2, PIK3CA or transformation into small cell histology (3%)." (PMID 26799287, 2017). "While tumour RAS status is undoubtedly a valuable predictive marker for response to EGFRIs, it remains important to investigate the roles of other potential biomarkers that could improve patient selection (e.g. epiregulin/amphiregulin, PIK3CA, PTEN)." (PMID 28424871, 2017). "The rate of pCR was similar among tumours with activation of the PI3K pathway (defined as a PIK3CA mutation and/or low PTEN expression and/or an ERBB family mutation) and among tumours without a PIK3CA or ERBB family mutation or low PTEN expression (44% vs. 50%; p = 0.769)." (PMID 28750640, 2017). "Our findings led to the hypothesis that the negative results of these clinical trials might come from the fact that patients were not selected according to tumor PIK3CA status." (PMID 27835884, 2016). "For example, modifications of EGFR and PIK3CA were almost clonal in tumour S6T1 but absent in S6T2." (PMID 27377421, 2016). "Finally, 4 patients with PIK3CA mutations in cfDNA, but not FFPE tumor samples, had simultaneous KRAS mutations in cfDNA and FFPE tumor samples." (PMID 25980577, 2015). "Of the single MSI-H tumor with an AKT1 mutation, PIK3CA and PTEN were not mutated." (PMID 26517354, 2015). "PAM pathway activation and PIK3CA mutation did not seem to correlate with clinicopathological features (menopause, histological grade, ER status, PR status, HER2 status, Ki67 expression, tumor size and lymph node involvement)." (PMID 25816324, 2015). "Based on these results we may conclude that patient #12, who contains an EGFR L858R mutation as well as a PIK3CA C420R mutation in the tumor DNA, may be less responsive to EGFR or PIK3CA inhibitors, but this has not yet been confirmed by clinical studies." (PMID 26068980, 2015).
tumor (continued). "Therefore, it is possible that TLK2 acts as a context-dependent driver of ER-positive/luminal tumours in the absence of PIK3CA expression." (PMID 26427375, 2015). "To elucidate the molecular mechanisms mediating tumor development in PIK3CA/Yap injected mice, we analyzed the key downstream signaling pathways of PI3K and Yap cascades in preneoplastic and neoplastic liver lesions from PIK3CA/Yap mice by immunohistochemistry." (PMID 25826091, 2015). "Hence, known oncogenic mutations in PIK3CA (exons 10 and 21) and AKT1 (exon 2) were screened in tumor DNA with negative results, which suggests that the responsible somatic event(s) is a different, uncommon one." (PMID 24498881, 2014). "Indeed, in all samples where we detected PIK3CA translocations, and where PIK3CA was not amplified, PIK3CA mRNA expression levels were the highest within the respective tumour types." (PMID 25204415, 2014). "As seen, we could only evaluate the PIK3CA-GS in two small cohorts, as correlative tumor collection is not standard in many clinical studies." (PMID 23301057, 2013). "Also when focusing on an array of tumor types rather than on a single disease entity, PIK3CA mutant cell lines, or cell line derived xenografts were found to be selectively sensitive to PI3K pathway inhibition." (PMID 22970424, 2012). "A comparable number of tumors from young (<50 years) and old patients (>70 years) was quadruple negative for the four predictive gene markers (KRAS-BRAF-PIK3CA-PTEN); however, 16% of young versus only 1% of the old patients had tumor mutations in PTEN/PIK3CA exclusively." (PMID 21103049, 2010). "Finally, the gene-set #2 also contained several tumour suppressors (EPHA3 and EPHB2) and proto-oncogenes (AKT1, AURKA, ETV6, MITF and PIK3CA), which expands on the observed enrichment of the immune response and suggests that this gene-set has a critical role in breast tumorigenesis." (PMID 19826428, 2009). "We show that PIK3CA upregulation occurs in non-proliferating tumor regions in vivo." (PMID 18335034, 2008). "For example, the promoter regions of genes such as PIK3CA and cyclin-dependent kinase inhibitor 2A (CDKN2A) show high levels of methylation in EBVaGC, which not only affects the expression of these genes but may also reduce metastatic potential by inhibiting tumor stemness." (PMID 41573653, 2025). "In addition, the PIK3CA-mutant tumor might respond well to the selective inhibition of PIK3CA, such as copanlisib or alpelisib, rather than PI3K inhibitors, since the activation event is selective." (PMID 40142329, 2025). "Molecular profiling testing revealed that tumor tissue was ER+ (90%), amplified for ERBB2 (HER2/neu), PR+, programmed death ligand 1-positive (IHC; Sp142), MS, NTRK fusion negative, AR mutation positive, BRCA1 and BRCA2 negative, PIK3CA mutated, and PTEN mutation positive." (PMID 39220641, 2024). "However, an exploratory analysis of the trial suggests that capivasertib may also be effective in PIK3CA/AKT/PTEN non-altered tumours." (PMID 39322687, 2024). "However, there is increasing evidence that genetic PI3K pathway activation in cancer might be a graded event, similar to observations of oncogenic K-Ras, with the presence of more than one mutant copy of PIK3CA and/or genetic activation of other PI3K pathway components seen in established tumours." (PMID 31374965, 2019).
tumor (continued). "Four of the right cases with undetectable ESR1 mutation at progression were also PIK3CA mutated at baseline and all of these had PIK3CA mutation detected at the end of treatment, indicating the observed loss of ESR1 mutation was not an artifact of low tumor content." (PMID 29497091, 2018). "However, downregulation of PIK3CA upon C-KRAS-esiRNA treatment could not be observed in different lysates of these tumor treatment groups in Western blots, whereas PIK3CA expression was significantly downregulated in C-PIK3CA-esiRNA treated tumors." (PMID 30001368, 2018). "Thus, PIK3CA, NRAS, HRAS, PTEN, MET, and IDH2 R140Q mutations might be related to the metastasis process rather than primary tumor development." (PMID 29290998, 2017). "Conversely, one case harbored a low level subclonal PIK3CA mutation that was discovered by a clinical genomics panel in the primary tumor, but was not identified by WES in different primary tumor blocks from the same case, nor in multiple samplings of the recurrent tumor." (PMID 29084603, 2017). "Whole exome sequencing of tumor obtained at time of progressive disease did not reveal secondary BRAF or RAS mutations, but did demonstrate a somatic gain-of-function PIK3CA mutation (H1047R) as well as a CDKN2A aberration, which may have been responsible for dabrafenib resistance." (PMID 23470635, 2013). "To further exclude the possibility of pathological misclassification of endometrioid, clear cell or LGS tumours in the mutation-negative cases, we also tested for mutations commonly associated with these subtypes in KRAS (exon 2), BRAF (exon 15), CTNNB1 (exon 3), and PIK3CA (exons 10 and 21)." (PMID 20229506, 2010). "Thus, PIK3CA-targeted cancer therapy might be a rational approach to target non-proliferating tumor cells and enhance the effect of chemotherapy or radiation in combinatorial therapy." (PMID 18335034, 2008). "Thus, stress signals mediated by these factors might regulate PIK3CA expression in non-proliferating tumor cells in areas of decreased vascularization and increased lymphocyte-infiltrating." (PMID 18335034, 2008). "Moreover, low tumor mitotic activity was associated with better prognosis in LUAD subgroups with EGFR mutations or pan-negative (no oncogenic alteration in genes including KRAS, EGFR, BRAF, ERBB2, PIK3CA, ALK, and ROS1) but not in those with KRAS or BRAF mutations." (PMID 41404730, 2025). "Tumor samples exhibited slightly higher expression than metastatic samples, suggesting that PI3K3CA is involved in tumorigenesis (As shown, MAP2K1 and PIK3CA expressions did not significantly increase in metastasis." (PMID 41009348, 2025). "More importantly, we reveal a relevant mechanism that PIK3CD, but not PIK3CA and PIK3CB, is transcriptionally regulated by the pro‐inflammatory IL2/JAK3/STAT5 axis and tumor‐infiltrating immune cells such as lymphocytes." (PMID 38545256, 2024). "When the analysis was restricted to PIK3CA, AKT and PTEN individually, activation of the signalling molecules was not different between wild-type and mutant tumours (p > 0.05; data not shown)." (PMID 39322687, 2024). "In BCM-4664 (PIK3CA-wild-type) PDX model, the addition of L-NMMA to alpelisib did not significantly reduce tumor volume relative to single-agent alpelisib therapy (p = 0.1275)." (PMID 39737957, 2024). "In detail, PTEN loss was determined via IHC using the absence of PTEN staining in 50% or more of the specimen’s tumor area; NGS to examine PTEN status or PIK3CA/AKT1/PTEN alteration was performed using a FoundationOne CDx NGS assay." (PMID 37894312, 2023).